TNF (tumor necrosis factor)
Diseases named in the same sentence as TNF in open-access papers (continued):
Sharing a sentence is not in itself a finding about the gene and the disease.
cancer (continued). "The history of TNF is closely related to the history of cancer immunotherapy." (PMID 33917839, 2021). "Correlation between survival and non-synonymous TNF pathway mutations was not discovered in any cancer type." (PMID 34367136, 2021). "A comparison of serum concentrations of four pro-inflammatory factors (e.g., IL-6, IL-1β, Chemokine (C-X-C Motif) Ligand 8(CXCL8)/IL-8, and TNF-α) in advanced-stage cancer patients showed that IL-1β levels correlated more strongly with clinical characteristics than those of IL-6." (PMID 33557173, 2021). "Signaling pathways such as proteoglycans in cancer, C-type lectin receptor signaling pathway, and TNF signaling pathway may have an important role in GA treatment with ARC." (PMID 33995019, 2021). "The innate immune cells of the TME secrete various cytokines such as TNF-α and interleukin-6 (IL-6), which can promote cancer cell survival and induce the expression of vascular endothelial cell adhesion molecules (CAM) that facilitate extravasation of leukocytes." (PMID 33986746, 2021). "TNF-α contributes to cancer development by generating chronic inflammation." (PMID 34571823, 2021). "Thus, we expected that TNFα treatment or NCOR1 knockdown contributed to overcoming tamoxifen tolerance by increasing the sensitivity of cancer cells to this drug." (PMID 34073371, 2021). "Indeed, TNF-α is involved in cancer promotion and progression, and pheophorbides have shown important antitumor activities." (PMID 34683379, 2021). "As an important inflammatory cytokine, TNF-α has been used in cancer therapies for decades." (PMID 33429846, 2021). "There are limited reports in the field of cancer and TNFα inhibitors." (PMID 33540543, 2021). "Tumor necrosis factor (TNF) can induce and stabilize PD-L1, driving cancer immune evasion." (PMID 34575983, 2021). "The use of immunotherapies for cancer treatment such as monoclonal antibodies against cancer cells or immune checkpoints and adoptive cell therapy, are beginning to broaden our understanding of TNFα’s actions and its potential therapeutic role." (PMID 33540543, 2021). "This cascade is active in many cancers, due to phosphorylation and inactivation of the NF-κB inhibitor IκBα, allowing the NF-κB p50-p65 heterodimer to enter the nucleus and drive transcription of proproliferative factors including TNF-α." (PMID 34497073, 2021). "All DEGs between MCAO and SHAM control groups were significantly (p < 0.05) enriched to 20 pathway terms with maximal enrichment (FDR < 0.05) for “cytokine-cytokine receptor interaction”, “proteoglycans in cancer”, “TNF signaling pathway”, and “MicroRNAs in cancer”." (PMID 34944656, 2021). "For biological process enrichment, the YTHDC2-related genes in LUAD and LUSC were also enriched in several cancer-related processes, including 'NF-κB signaling', 'mRNA splicing', 'cell cycle', 'cell division', 'TNF-mediated signaling' and 'Wnt signaling pathway'." (PMID 34326699, 2021). "Naringenin, a major citrus peel flavonoid was also found to suppress the upregulation of matrix metalloproteinase-9 as well as tumor necrosis factor-α which mediated the release of IL-6 and IL-8 posing a potential impact on cancer cell migration and metastasis." (PMID 33782546, 2021). "Overexpression of TNFα was not linked with significant affection of the subpopulation of cancer stem-like cells in vitro." (PMID 33957885, 2021). "In general, cancer cells during the transformation process selectively sacrifice at least some elements of their potent innate antiviral response pathways mediated by cytokines like type I and II interferons (IFNs) or tumor necrosis factor (TNF)." (PMID 34771615, 2021).
cancer (continued). "Furthermore, KEGG pathway mainly enriched in inflammation related pathways, such as TNF signaling pathway, chemokine signaling pathway, ribosome, pathway in cancer." (PMID 33961683, 2021). "Moreover, KEGG enrichment analysis also indicated that these genes primarily participated in cancer pathways, protein processing in the endoplasmic reticulum, as well as the TNF signaling pathway." (PMID 33976960, 2021). "However, the cancer cells escape omentin-1 mediated anti-invasive barrier by downregulating its expression in mesothelial cells through TNF-α signaling." (PMID 34588926, 2021). "TNF-α is a negative regulator of adipocytes and well-known factor of cancer cachexia." (PMID 34502316, 2021). "This phenomenon could be prevented through the actions of FAT10 protein that induces the activity of TNF-α during cancer pathogenesis by disrupting the cell cycle, chromosomal instability, and inhibition of apoptosis." (PMID 34571823, 2021). "There is plenty of evidence that TNFα upregulates PD-L1 expression in several cancer types." (PMID 33540543, 2021). "In another study, the risk of malignancy and mortality was higher in elderly patients treated with TP than in those with anti-TNF therapy (H= 3.017; 95% CI: 1.050–8.666; p = 0.0403 and HR= 3.682; 95% CI: 1.192–11.377; p = 0.0235, for malignancy and mortality, respectively)." (PMID 34336887, 2021). "In tumor microenvironment, the chaotic interplay between cancer and host cells may lead to an increase of factors and cytokines such as TNFα, IL-6, PTHrp which eventually results in an impaired muscle homeostasis." (PMID 33804536, 2021). "Because IFN-γ and TNFα induce senescence in numerous murine and human cancers, this may be a general mechanism for arresting cancer progression." (PMID 34445397, 2021). "Finally, the involvement of SOCS1, TAB2, and Foxp3 as direct targets for TNF-α gene in both cancer types was assessed." (PMID 34900737, 2021). "Therefore, TNF blockers have been used to ameliorate the immune-related adverse events in patients undergoing cancer treatment with immune checkpoint inhibitors (ICIs)." (PMID 33801589, 2021). "Finally, we hope that we can collect more cancer types to validate the role of TNFα signaling on the prognosis related to immunotherapy." (PMID 34603277, 2021). "Diabetes involves metabolic alterations, hormonal imbalances particularly of insulin/insulin growth factor-1 and adiponectin/ leptin, and immune response such as elevated levels of pro-inflammatory cytokines like tumor necrosis factor-a (TNF-α), and all these features it shares with cancer." (PMID 34225729, 2021). "The uses of TNF-α in cancer treatment and to facilitate cancer drug delivery are discussed." (PMID 33986746, 2021). "Moreover, the long-term use of biologics raises safety concerns, such as monoclonal-antibody-based TNF-alpha inhibitors (anti-TNF-α) and cancer." (PMID 34209234, 2021). "In this review we highlight recent data pointing out TNFα participation in the effectiveness of monoclonal antibodies (mAbs) targeting cancer cells, immune checkpoint inhibitors, and adoptive cell therapy (ACT), as well as its involvement in the adverse immune effects of immunotherapy." (PMID 33540543, 2021). "Moreover, it is also well-known that IFN-γ acts as an important stimulus for skewing the Mφ phenotype into the M1 type, which exerts its anti-cancer efficacy through immune mediators, specifically iNOS, TNF, and IL-6." (PMID 34202080, 2021). "Cell cycle, FoxO, pathways in cancer and DNA repair related pathways were the most significantly enriched signalling pathways in mechanically stretched hSCO whereas TNF, cytokine–cytokine interactions, PI3K-AKT, Jak-STAT, HIF-1 were mostly enriched in murine cells." (PMID 34099736, 2021). "The bidirectional regulatory effect of TNF-α on tumors also plays a key role in cancer progression." (PMID 35069596, 2021).
cancer (continued). "After these factors have been activated, they could lead to the recruitment of macrophages mediated by the expression of cytokines and chemokines (TNF-α and IL-6) of cancer cells." (PMID 34965886, 2021). "In addition, we demonstrated that the cells resistant to anti-cancer drugs (CASP3/7/6 and FADD-deficient cells) are sensitive to treatment with TNF-α/SM, which triggers RIP1-dependent necroptosis." (PMID 33800107, 2021). "Single-cell analysis identified that CTSC and B2M were up-regulated in LNM-positive epithelial cells with strong correlation to poor DFS, suggesting that cancer-related signaling pathways such as TNF-α/p38 MAPK signaling pathway could promote LNM in PTC." (PMID 34805166, 2021). "As a whole, the complexity of the transcription regulatory mechanism increased as the response time to TNF stimulation decreased, indicating that inflammation and cancer-related ERGs require a strict and precise transcriptional regulation to avoid overproduction." (PMID 34853340, 2021). "In addition, overproduction of TNF-α is correlated with the development of multiple diseases, including cancer." (PMID 34451892, 2021). "Furthermore, TNF-α is involved in apoptosis, cell survival, and inflammation, and is a potential target for cancer therapy." (PMID 33668827, 2021). "TNF-α is a major factor in inflammation and cancer progression." (PMID 33966638, 2021). "Inflammation can be developed by a huge variety of diseases, including obesity, hyperglycemia, and excessive lipid accumulation, which can promote different types of cancers by releasing several factors such as ROS, TNF-α, IL-1, IL-6, IL-8, COX2, iNOS, and chemokines, among many others." (PMID 34202969, 2021). "Finally, TNF-α can inhibit the apoptosis of PDAC cells by activating NF-kB, an important transcription factor that has been implicated in many different cancers." (PMID 34940031, 2021). "TNF-α, another critical inflammatory mediator, plays a significant role in cancer cachexia." (PMID 34627306, 2021). "Interestingly, two candidate pathways were included, TNF and MAPK signaling pathways associated with the inflammatory processes in cancer." (PMID 34490085, 2021). "However, the ethanolic CN extracts prevented the smoldering inflammation between cancer cells and immune cells by reducing the level of pro-inflammatory cytokines, such as IL-6, IL-1β and TNF-α." (PMID 34379689, 2021). "TNFα is a pleiotropic autocrine and paracrine mediator important in multiple signaling cascades that range from activating immune cells to fight viruses, bacteria, and cancer cells, to promoting entry of monocytes and lymphocytes into atherosclerotic lesions." (PMID 34207810, 2021). "Several proinflammatory cytokines, including IL-1, IL-6, and TNF-α, may have important roles in the pathological mechanisms of cancer cachexia." (PMID 34502316, 2021). "TNFα has been described as having contradictory effects on almost every type of cancer." (PMID 33540543, 2021). "We could assume that TNF-α enhances the invasion and metastasis ability of cancer cells via the NF-κB signalling pathway." (PMID 33776564, 2021). "We found that recombinant IFN-γ could dose-dependently inhibit A549 cancer cell proliferation (21.9% vs. 28.1%), while TNF-α showed less effect (5.5% and 12.6%)." (PMID 33175182, 2021). "The role of physical exercise was also shown to improve T cell responses, increasing both NK and CD8+ T cell mobilization into the blood, migration into the tissues, and TNF activation of these cells, and this is known to be the mechanism by which physical exercise confers protection against cancer." (PMID 33613573, 2021). "TNF-α seems to play a controversial role in cancer progression in IBD." (PMID 34884543, 2021).
cancer (continued). "TNF is also present in the TIME of many cancers, where it is thought to enhance cancer growth." (PMID 34867972, 2021). "Modulation of TNF levels by microbiota and vice versa may be an important component in the therapy of intestinal inflammation and inflammation-induced cancer." (PMID 33917839, 2021). "Similarly, the present meta-analysis observed that the odds of cancer were 1.36 times higher in the anti-TNFα agent treatment group (95% CI: 1.20–1.53, p < 0.00001)." (PMID 34790122, 2021). "Due to all the beneficial effects of TNF-α during cancer development, targeting TNF-α might be a useful strategy for OSCC treatment." (PMID 35047997, 2021). "Furthermore, clinical studies have shown that the expression level of TNF-α in serum samples acquired from patients with NSCLC increased with the stage of cancer." (PMID 32802118, 2020). "A number of immune-related genes were expanded in two buried bivalves, including interferon-inducible GTPase 5 (Iigp5) and heat shock protein 70 (Hsp70) member 12 (Hsp70_12), and they were enriched in “TNF signaling pathway” and “proteoglycans in cancer,” respectively." (PMID 32454450, 2020). "Network analysis indicated that main targets of main active components of TWH were target genes such as VEGFA, MAPK8 and CASP3, which are involved in the regulation of cancer pathway, TNF signal pathway, hepatitis B pathway, apoptosis pathway, NF-kappa B signal pathway and so forth." (PMID 32293395, 2020). "However, the anti-cancer effects of AIMs were significantly diminished by TNF-α treatment in terms of proliferation." (PMID 33233701, 2020). "Interleukin-6 and TNFα are important mediators that link inflammation and cancer." (PMID 32317968, 2020). "Furthermore, TAMs upregulate PD-L1 expression by assuming aerobic glycolysis while also secreting TNFα that promotes aerobic glycolysis in cancer cells and augments PD-L1 expression on myeloid cells." (PMID 32992658, 2020). "Additionally, we comprehensively assessed the causal associations of TNF levels with a broad range of CVD and cancer outcomes." (PMID 32805626, 2020). "Cancer cells produce soluble factors, such as cytokines—for example, interleukin-6 (IL-6), IL-11, tumor necrosis factor alpha (TNF-α), and receptor activator of nuclear factor kappa-Β ligand (RANKL)—that activate osteoclastogenesis, leading to bone degradation." (PMID 33659950, 2020). "TNF-α is an inflammatory cytokine, and its role in cancer is complicated." (PMID 33680949, 2020). "In addition to generating immunosuppressive cytokines, TAMs produce proinflammatory cytokines including TNFα, IL-1, and IL-6 that initiate NF-κB signal transduction, which is a critical factor in cancer cell inflammation." (PMID 33256011, 2020). "In addition, research showed that SM-induced loss of cIAP1/2, two critical regulators of the TNF receptor superfamily and NF-κB signaling, sensitizes cancer cells to TNFα- or TRAIL-mediated death." (PMID 32325691, 2020). "The information here presented postulates TNFα as a central player in cancer initiation, progression, invasion and metastasis, and proposes it as an attractive therapeutic target for the benefit of cancer patients." (PMID 32391269, 2020). "However, SMs can undermine this TNF-α dependency of TN-BCs and promote TNF-induced killing of those cancers even though there is a relative reduction in the death effector levels." (PMID 32393742, 2020). "In addition, TNF-α is highly expressed in advanced cancer, and the TNF-α inhibitor shows anti-cancer effects by inhibiting cancer metastasis." (PMID 32455624, 2020).
cancer (continued). "They concluded that these cancer-promoting effects of vagal denervation occur due to the removed anti-inflammatory processes and subsequently, overproduction of inflammatory cytokines such as TNF-α in pancreatic tissue." (PMID 32215331, 2020). "In addition, the KEGG heatmap of the differentially expressed miRNAs were involved in multiple pathways, including proteoglycans in cancer, TNF signaling pathway, and TGF-β signaling pathway." (PMID 32596357, 2020). "The dysregulation of TNF genes are involved in almost all types of cancer." (PMID 33024622, 2020). "Th17 cells are polyfunctional in cancer, secreting IL-2, tumor necrosis factor, and IFN-γ." (PMID 32104586, 2020). "Moreover, cancer cells with BRAF mutation inhibit the maturation of dendritic cells and, thus, the production of TNF-α and IL-12." (PMID 33171792, 2020). "Overall, DN052 was more potent than motolimod in inducing the cytokines including INF-γ, IL-12p40, TNF-α which were reported to be predictive of clinical benefit in motolimod-treated cancer patients suggesting DN052 may have superior efficacy in humans." (PMID 35006413, 2020). "TNFα promotes cancer cell growth, angiogenesis, metastasis and apoptosis." (PMID 32194778, 2020). "Therefore, therapeutic approaches manipulating TNFα in cancer should be interpreted with great caution." (PMID 32219066, 2020). "Therefore, our results provide additional confirmation of the impaired TNFα-mediated cytotoxic activity of DCs in patients with malignant tumors." (PMID 32326230, 2020). "Significant progress is made to inhibit cancer growth through manipulating TNF-α expression." (PMID 33262947, 2020). "TNF-α is also involved in pathological processes, such as chronic inflammation and malignant disease, and may be a target molecule for cancer therapy." (PMID 33009434, 2020). "Moreover, repeated intravenous administrations of RGD4C/AAVP carrying tumor necrosis factor alpha (TNFα), once a week over eight weeks, proved safe in dogs with natural cancers." (PMID 33114050, 2020). "To further test this hypothesis, we treated cancer cells with takinib + TNF (30 ng/mL) combination therapy." (PMID 32523651, 2020). "The KEGG pathway, cross talking with multiple pathways, especially proteoglycans in cancer, TNF signaling pathway and TGF-β signaling pathway, may contribute to tumorigenesis/cancer progression." (PMID 32596357, 2020). "In cancer patients, release of proinflammatory cytokines (IL‐6, TNF) and catabolic factors may also play a more important role for these findings." (PMID 35847697, 2020). "Altogether, TNFα also carries the potential to mount antitumoral responses in cancer therapy." (PMID 32733461, 2020). "High levels of TNF-α are found in cancer and non-cancer proinflammatory environments." (PMID 32655574, 2020). "TNF-α was demonstrated as inducer of cell migration in cancer cells." (PMID 32670264, 2020). "It is known to be upregulated in inflammatory conditions such as malignant tumor expansion since it results in neo-capillary formation; cancers may be relatively benign until factors, yet to be identified, induce TNF production." (PMID 32019214, 2020). "A number of paradoxical effects have been reported indicating that TNF-α may act either as a suppressor or as a stimulator of cancer progression." (PMID 33202705, 2020). "The anti-cancer mechanism of violacein appears to mimic the activities of tumor necrosis factor α (TNF-α) in signaling cellular apoptosis through the activation of caspase 8, transcription of nuclear factor kappaB (NF-κB), and p38 mitogen-activated protein (MAP) kinase." (PMID 33364537, 2020). "TNF-α was used to stimulate cells in order to check the cancer cell invasion." (PMID 33233701, 2020). "In addition, EGCG is known to lead to the induction of apoptosis in cancer cells by inhibiting tumor necrosis factor α activity (TNF-α)." (PMID 32143309, 2020).